Y_RNA (Y RNA )
Gene: Miscellaneous RNA gene on chromosome 12 (123,348,999 to 123,349,100, reverse strand). Ensembl gene ENSG00000207189.
Homologues: Orthologues: chimpanzee Y_RNA (97% identical). Paralogues in human: RNY3 (88% identical), Y_RNA (87% identical), Y_RNA (86% identical), RNY3P1 (85% identical), Y_RNA (85% identical), RNY3P14 (84% identical), Y_RNA (84% identical), RNY3P16 (83% identical), Y_RNA (83% identical), RNY3P11 (82% identical), RNY3P4 (82% identical), RNY3P5 (82% identical), and 93 more.